PDX1 (pancreatic and duodenal homeobox 1)
Diseases named in the same sentence as PDX1 in open-access papers (continued):
Sharing a sentence is not in itself a finding about the gene and the disease.
cancer (continued). "We conclude that ectopic expression of PDX1 reduces the migration potential of cancer cells, by increasing the adhesive properties of cells and reducing the sensitivity to TGFβ1-induced EMT." (PMID 34503200, 2021). "The data obtained suggest that ectopic expression of PDX1 reduces the migration potential of cancer cells, in particular, by increasing the adhesive properties of cells and reducing the sensitivity of cells to TGFβ1-induced EMT." (PMID 34503200, 2021). "This genetic strategy allows Pdx1‐lineage cancer cells to express EGFP, while cells that activate αSMA or Fsp1 promoters are positive for tdTomato." (PMID 30120146, 2018). "According to the genomic locations, the 20 probes were associated to 39 genes including well-known cancer-related genes, such as TP73, PDX1, and FUT8." (PMID 28951630, 2017). "These genes related to the selected probes are mostly associated with cancer and LN metastasis, such as TP73, PDX1, FUT8, HOXD1, NMT1, and SEMA3E." (PMID 28951630, 2017). "PDX-1 is aberrantly overexpressed in a variety of human cancers including pancreatic, gastric, liver, colon, breast, prostate, kidney, lung, and ovarian cancer and pancreatic neuroendocrine tumor." (PMID 25009500, 2014). "It was shown that ATF3, a Wnt/β-catenin target gene in cancer cell lines, can either transcriptionally repress Pdx1 expression or physically interact with PDX1 to block PDX1 mediated transactivation in a murine β-cell line." (PMID 23741453, 2013). "PDX1 is implicated in several cancers, although it is not uniformly a tumor suppressor or an oncoprotein." (PMID 36272648, 2022). "This may indicate a role of PDX1 in promoting cell cycle transition from G1 to S stage and simultaneously slowing down cancer cell motility and migration." (PMID 34503200, 2021). "The Pdx1‐lineage cancer cells express EGFP, while αSMA‐positive myofibroblasts express tdTomato." (PMID 30120146, 2018). "Neutralizing antibodies to IL-6 or histone H3 or knockout of the receptor for advanced glycation end products all limit K-Ras signaling activation, prevent cancer development and metastasis/invasion, and prolong animal survival in Pdx1-Cre;K-RasG12D/+;Hmgb1−/− mice." (PMID 28374746, 2017). "Moreover, PDX-1 overexpression in patients with cancers is significantly correlated with the pathological parameters (e.g., metastasis and histological grade)." (PMID 25009500, 2014). "Identification of PDX-1 as a transcriptional target for SSTR5 may help in guiding the choice of therapeutic cancer treatments." (PMID 25009500, 2014). "The appearance of new mutations in PDX1 might be the consequence of some degree of clonal selection during in vivo growth, since mutations of ARID1A are associated with increased cellular proliferation and have been reported in a variety of human cancers." (PMID 31216647, 2019). "TF RNF146 could positively regulate target gene PDX1 to inhibit the proliferation of cancer cells." (PMID 31126066, 2019). "The feature selection procedure extracted several cancer-related and lymph node metastasis-related genes, such as TP73, PDX1, FUT8, HOXD1, NMT1, and SEMA3E." (PMID 28951630, 2017). "For other genes or regions, e.g. DLX5, GRASP Region 3, IRX1, MMP2, NPY, PDX1 and TCF21, significant levels of methylation were evident in the matched normal tissue but methylation was always significantly increased in the cancer tissue." (PMID 24485021, 2014).
cancer (continued). "We blocked the secretion of exosomes by conditionally knocking out (KO) Rab27a in the healthy pancreas (Pdx1-Flp; Rab27aFrt/Frt) and in PDAC cancer cells using the fast progression PDAC model (PKT iRab27a, Ptf1a-Cre; LSL-KrasG12D/+; Tgfbr2loxP/loxP; R26LSL-FLPoERT2/+; Rab27aFrt/Frt)." (PMID 38383468, 2024). "Our study highlights a potential narrow window for the therapeutic application of PDX1 as an antimetastatic agent in the initial stages of cancer development in patients that are without early metastasis." (PMID 34503200, 2021).
infection (18 papers, 2008 to 2021). The state of being infected such as from the introduction of a foreign agent such as serum, vaccine, antigenic substance or organism. "In this study, we also evaluated the expression of VB6 de novo (PDX2, PDX1.2, PDX 1.1) and the salvage pathway genes (ATPLR) and GST antioxidant gene in the pdx1.3 mutant line, and in the wild type before and after infection." (PMID 32670323, 2020). "The increase in the transcript abundance of PDX1 was evident upon infection of tobacco leaves with P. syringae pv." (PMID 29466404, 2018). "In the converse approach, the infection of islets with AdSirt6 increased mRNA and protein levels of Glut2, GK, and Pdx1 and decreased FoxO1 protein expression, indicating the presence of a causal relationship between Sirt6 and FoxO1-Pdx1-Glut2." (PMID 27457971, 2016). "Remarkably, the ectopic expression of Pdx-1, Ngn-3 and Maf-A in hMSCs, combined with infection with HAdV.EF1α.DsRed.F50, increased glucagon gene expression up to 100-fold." (PMID 23110179, 2012). "In conclusion, our findings demonstrated that genetic manipulation producing infection by a combination of PDX-1 NeuroD1, and MafA and their subsequent expression significantly promoted insulin-producing function of mMSCs." (PMID 22761608, 2012). "Although hMSC have previously been shown to express insulin at mRNA level with the infection of recombinant Pdx-1 adenovirus, only a small number of MSCs became insulin positive cells when no gene modification had taken place." (PMID 18628974, 2008). "Notably, a shift in the normalized distribution of PDX1 fluorescence was detected beginning at 24 hrs post-infection, which persisted until 120 hrs." (PMID 33514698, 2021). "The ratios of nGFP-positive cells at 24 hours after infection with the indicated vector at an optimal multiplicity of infection (MOI) were as follows: 94.1% ± 4.5% for pAd-Pdx1; 88.8% ± 7.6% for pAd-Ngn3; 88.6% ± 3.1% for pAd-NeuroD1; and 87.7% ± 4.2% for pAd-MafA." (PMID 29768476, 2018). "However, the reporter gene activity had disappeared by 14 days after the infection, indicating that the β-like cell conversion by Pdx1/NeuroD/MafA gene transfer was transient or incomplete." (PMID 23593212, 2013). "At 3days after infection, selective increases in the mRNA levels of insulin I (Ins1) and insulin II (Ins2) were observed in the cells that had been infected with a triple combination of adenovirus (Pdx1 and MafA, with either Ngn3 or NeuroD1) in a semiquantitative RT-PCR analysis." (PMID 29768476, 2018). "After transducing PDX1 sgRNAs, we isolated GFP+ human islet cells 6 days after infection, and performed TIDE PCR and digital droplet (dd)PCR with gene-specific probes to genomic DNA (n = 3 independent donors)." (PMID 33893274, 2021). "We transferred a 3-gene combination of Pdx1, Neurod, and Mafa into the MIP-Luc-VU mice with different infectious titers to detect the bioluminescence signal 3 days after infection, according to a previous study." (PMID 25397325, 2014). "The Pdx1, NeuroD, and MafA genes were transferred by adenovirus vectors, and serial BLI was monitored before and after infection." (PMID 23593212, 2013). "Transcripts for canonical β-cell markers including PDX1, FOXA2, G6PC2, and PAX6 were present at low levels and also decreased following infection but were not amongst the top 1000 differentially expressed transcripts." (PMID 32093375, 2020).
adenocarcinoma (6 papers, 2010 to 2022). A common cancer characterized by the presence of malignant glandular cells.
metabolic disease (3 papers, 2017 to 2020). A congenital disorder (due to inherited enzyme abnormality) or acquired (due to failure of a metabolically important organ) disorder resulting from an abnormal metabolic process. "PDX1 is highly conserved across vertebrates, and PDX1 mutations have been linked to metabolic disease in humans." (PMID 33076817, 2020). "Pyrosequencing analyses were performed for the candidate genes KCNJ11, PPARγ, PDK4, KCNQ1, SCD1, PDX1, FTO and PEG3 in peripheral blood leukocytes (PBLs) from 25 patients diagnosed with only T2D, 9 patients diagnosed with T2D and MetS and 11 control subjects without any metabolic disorders." (PMID 28727822, 2017).
inflammation (2 papers, 2016 to 2022). Aberrant reaction of the microcirculation characterized by movement of fluid and leukocytes from the blood into extravascular tissues. "Specifically, we utilized a genetically engineered mouse model (GEMM) harboring a pancreas specific Kras mutation (KrasG12D; pdx1-Cre mice) and treated these animals with caerulein, a well-established inducer of pancreatic inflammation." (PMID 26697077, 2016).
retinopathy (1 paper, 2023). "Zebrafish lacking Pdx1 (pdx1−/− mutants) have reduced numbers of β cells as larvae, and the few fish that survive to adulthood display elevated blood glucose levels and retinopathy However, it is hard to separate symptoms caused by chronic diabetes from developmental defects." (PMID 37401381, 2023).
PDX1 also shares sentences with these, for which no sentence is quoted: maturity-onset diabetes of the young (4 papers); diabetic nephropathy (3); Atrophy (2); Cachexia (2); Cerebellar hypoplasia (2); dyslipidemia (2); Hypoinsulinemia (2); hypothyroidism (2); intraepithelial neoplasia (2); IPEX syndrome (2); lung (2); melanoma (2); Stroke (2); Wolcott-Rallison syndrome (2); Allergy (1); amyloidosis (1); Arthritis (1); bacteremia (1); basal cell carcinoma (1); breast tumors (1); campomelic dysplasia (1); cerebellar agenesis (1); cholangiocarcinoma (1); Cholestatic liver disease (1); clear renal cell carcinoma (1); cleidocranial dysplasia (1); colorectal NETs (1); congenital hypothyroidism (1); cystadenoma (1); duodenal atresia (1).
A further 46 diseases each share a sentence with PDX1 in 1 paper.